CGAS (cyclic GMP-AMP synthase)
Diseases named in the same sentence as CGAS in open-access papers (continued):
Sharing a sentence is not in itself a finding about the gene and the disease.
infection (480 papers, 2015 to 2026). The state of being infected such as from the introduction of a foreign agent such as serum, vaccine, antigenic substance or organism. "Firstly, this system represents a high-risk domain for various pathological processes, including infection, inflammation, metabolic disorders, and tissue damage, thereby offering diverse activation scenarios for the cGAS-STING pathway." (PMID 41041344, 2025). "Here, rabies in cGAS-deficient (cGAS-/-) mice was less severe than wild-type (WT) mice at 7 days post-infection, as indicated by viral burdens in hippocampus, blood–brain barrier defect, and inflammatory gene expression." (PMID 41300373, 2025). "In response to infection, cGAS can recognize pathogenic dsDNAs and then induce the production of second messenger cyclic GMP‐AMP (cGAMP), which subsequently activates STING located on the endoplasmic reticulum." (PMID 41395239, 2025). "Normally, STING is activated through cGAS; however, gain-of-function mutations disrupt normal immune development, impairing infection defense and driving pathological inflammation." (PMID 41153813, 2025). "We report that HCMV expressing a protein-S-nitrosylation-deficient pp65 is resistant to the activation of cGAS in the infection of primary dermal fibroblasts." (PMID 40243337, 2025). "In response to infections, cGAS detects pathogenic cytosolic dsDNA to produce cyclic GMP–AMP (cGAMP) and activate STING." (PMID 40645668, 2025). "The inhibitory effect of cGAS palmitoylation in antiviral responses has been observed in vivo where mice deficient in ZDHHC18 are resistant to the infection of HSV-1." (PMID 38675916, 2024). "In both cases, expression of degradation-defective cGAS mutants reduced the susceptibility of cells to infection and increased the expression of type I IFN." (PMID 38418882, 2024). "Following infection of host cells by pathogenic microorganisms, cGAS as a crucial DNA sensor, quickly identifies and detects foreign viral DNA in the cytoplasm, leading to the formation of a 2 : 2 dimer and the generation of 2′,3′-cGAMP." (PMID 40303074, 2024). "Since our model so far indicates the contribution of cGAS-generated 2′-3′ cGAMPs in the activation of STING during infection, we next determined the effect of cGAS on C. burnetii infection using WT and cGAS-deficient (cGAS−/−) BMDMs." (PMID 38459007, 2024). "By contrast, enforced degradation of cGAS by SPSB3 overexpression increased the susceptibility of the cells to infection with both HSV-1 and VACV." (PMID 38418882, 2024). "The cGAS-STING pathway is a conserved innate immune mechanism that responds to pathogenic infections, DNA damage, and aberrant cell activities like uncontrolled replication or senescence." (PMID 39737190, 2024). "Cytosolic DNA during pathogenic infection or from leakage of host cell nuclear or mitochondrial DNA binds to cGAS, which then metabolizes 2′,3′-cGAMPs to activate STING and its downstream signaling." (PMID 38459007, 2024). "cGAS recognizes pathogenic DNA from DNA and RNA viruses, activating innate immune cells and inducing essential immune responses against infection." (PMID 37354378, 2023). "Silica, smoking, and pathogenic infection can induce cell death and release self-DNA, leading to the activation of the cGAS-STING pathway and driving IFN-dependent sterile inflammation." (PMID 37122745, 2023). "Studies have shown that cGAS or STING-deficient mice are more susceptible to lethal infection after exposure to various DNA viruses, including herpes simplex virus 1 and ectromelia virus." (PMID 36733488, 2023). "Effective activation of cGAS within the innate immune pathway is crucial for countering exogenous pathogenic infections." (PMID 37920470, 2023). "Numerous DNA viruses activate the cGAS–STING pathway, and cGAS-deficient mice are more susceptible to lethal infection after exposure to many DNA viruses, namely, herpes simplex virus 1 (HSV-1), vaccinia virus (VACV), and murine gammaherpesvirus 68 (MHV68)." (PMID 35558078, 2022).
infection (continued). "With respect to infections caused by protozoan parasites, stimulation of the cGAS-STING-TBK1 pathway can yield detrimental or protective outcomes." (PMID 36405710, 2022). "West Nile virus is a single-stranded RNA virus, but cGas-/- mice are significantly more susceptible to infection compared to wildtype controls." (PMID 35185917, 2022). "cGAS knockout mice were more susceptible to infection with West Nile virus, a member of the flaviviruses." (PMID 34648591, 2021). "As an important sensor of innate immunity, cGAS–STING controls infection caused by pathogenic microorganisms in multiple ways, including the induction of type I IFN production, the activation of inflammatory responses, and triggering autophagy." (PMID 34926445, 2021). "The cGAS-STING pathway is an important component of the innate immunity against pathogen infection, with the fact that cGAS or STING deficiency mice are unable to induce type I interferon and susceptible to DNA viruses or Listeria monocytogenes." (PMID 33720974, 2021). "We conclude that UL138 inhibits innate immune signaling during HCMV productive infection of fibroblasts with a laboratory strain virus despite the presence of nine additional virally encoded cGAS/STING/TBK1 pathway antagonists." (PMID 34903048, 2021). "HCMV sustains its attack on cGAS-STING signaling through late times of infection through the expression of pUL31, a protein encoded a ‘true late’ times of infection." (PMID 34440891, 2021). "We conclude that UL138 inhibits innate immune signaling during HCMV productive infection of fibroblasts with a clinical strain virus despite the presence of at least nine additional virally encoded cGAS/STING/TBK1 pathway antagonists." (PMID 34903048, 2021). "In this context, cGAS is required for responding to DNA virus infection and cGAS deficient mice are more susceptible to infection with numerous DNA viruses, including herpes simplex cytomegalovirus and vaccinia virus." (PMID 35011636, 2021). "With the myriad cell types HCMV infects, as well as the three different infection programs (productive, persistent, and latent), encoding multiple cGAS/STING/TBK1 pathway inhibitors likely provides flexibility and insurance." (PMID 34903048, 2021). "Loss of Banf1 expression was associated with reduced infection of RNA and DNA viruses, and the enhanced expression of ISGs was mediated by a pathway requiring cGAS, STING, and IRF3." (PMID 32156810, 2020). "A similar effect was also observed in human BJ-5ta cells, wherein the disruption of cGAS gene led to an increased percentage of GFP-positive cells in two independent knockout clones after infection with a lentivirus encoding GFP." (PMID 32283527, 2020). "Together, these findings demonstrate that early sensing of virus by BMD cells via cGAS is critical to control a highly pathogenic DNA viral infection, and highlights the importance that curbing virus spread from the initial site of infection." (PMID 31877196, 2019). "This intercellular transfer of free or packaged cGAMP permits uninfected cells to mount a preventive IFN response, protecting them from infection or providing a faster response to DNA viruses that encode cGAS antagonists." (PMID 31426357, 2019). "We further show that cGAMP administration at the site of infection prevents lethal mousepox in cGAS deficient mice by curbing virus spread through the induction of IFN-I and ISGs." (PMID 31877196, 2019). "cGAS-deficient cells are also impaired in their response to infection with the cytosolic DNA virus MVA, as measured by CCL5 mRNA induction." (PMID 28194029, 2017). "In this work, we demonstrate that a defective cGAS–STING pathway renders mice highly susceptible to HSE-related disease after infection at an epithelial surface in the periphery." (PMID 27830700, 2016). "Of relevance to cellular immunity, both the antiviral ND10 body complex and the DNA sensor cGAS were PY-enriched associations during infection." (PMID 27935834, 2016).
infection (continued). "However, our research found the new function and mechanism of H1.2 in anti-infection immune regulation and confirmed H1.2 as an important negative regulatory molecule responsible for inhibition of cGAS, the important sensor in pathogenic recognition." (PMID 41972757, 2026). "Because cGAS is the receptor for DNAs, particularly for host genomic DNA and mtDNA, which are among the important damage-associated molecular patterns (DAMPs) that alert innate immunity to the possible infection in the body." (PMID 40507879, 2025). "To probe the relevance of heightened type I IFN signalling, we infected HeLa CGAS-KO cells reconstituted with either WT cGAS or degradation-defective cGAS variants at a low multiplicity of infection with the DNA viruses herpes simplex virus-1 (HSV-1) and vaccinia virus (VACV)." (PMID 38418882, 2024). "Interestingly, infections with RNA viruses, such as Dengue virus, can activate the cGAS-STING and TLR9 pathways by causing mitochondrial stress and oxidized mtDNA release." (PMID 37325622, 2023). "Moreover, infection with certain RNA viruses causes mtDNA release from mitochondria into the cytosol, which triggers the innate immune response via the cGAS-MITA/STING axis." (PMID 37932533, 2023). "For instance, a study in vivo has shown that infection with herpes simplex virus type 1 (HSV-1) could cause brain immune cells to undergo cGAS-STING pathway-dependent apoptosis." (PMID 36769349, 2023). "Meanwhile, several proteins encoded by ASFV could antagonize cGAS-STING signaling pathway through different mechanisms for efficient infection and replication." (PMID 37228597, 2023). "Infection by UL12-deficient HSV-1 strains results in reduced cGAS–STING signaling and infection compared to wild-type HSV-1, strongly suggesting that cytosolic mtDNA release activates cGAS–STING signaling during HSV-1 infection and provides antiviral resistance in vivo." (PMID 37001140, 2023). "The post-translational regulation of cGAS during any pathogenic insult may either activate or deregulate the cGAS-STING signaling post-infection." (PMID 36139387, 2022). "Cytoplasmic DNA, typically a hallmark of pathogen infection, activates the cytosolic DNA‐sensing cGAS‐STING pathway that in turn drives the type I interferon (IFN) pathway and pro‐inflammatory cytokine production to induce the innate immune response against invading pathogens." (PMID 35278036, 2022). "Using an acute mouse infection model, we observed that deficiency of Cgas or Sting drastically reduced the production of IFNβ in both the liver and peripheral blood, indicating that the cGAS-STING axis is essential for the induction of the type I IFN response." (PMID 35108342, 2022). "However, cGAS-STING suggests a novel route to cause neuroinflammation through infection-activated microglia, triggering the NF-κB pathway and other inflammasomes, as the primary driver of AD." (PMID 35741054, 2022). "Notably, in EBSS-treated cells, PCV2 infection further increased the K48-linked poly-ubiquitination of cGAS, resulting in more cGAS degradation relative to that of mock infection." (PMID 34543359, 2021). "In addition to infection-associated DNA, cGAS can also detect endogenous self-DNA that gains access to the cytosol in the context of cell damage or stress." (PMID 35011636, 2021). "In addition, mitochondrial DNA can elicit the stimulation of the IFN-β promoter by cGAS, acting as a danger associated molecular pattern leaked during infection of dengue virus." (PMID 31940818, 2020). "Furthermore, we showed that ISG expression is lower in cGAS deficient human microglia both at rest and following infection with HSV-1." (PMID 33042875, 2020). "To demonstrate the specificity of Nu7441 in vivo, we performed similar infection experiments with cGAS-deficient mice and found that the immune-stimulatory effect of Nu7441 could not be observed." (PMID 33273464, 2020).
infection (continued). "Moreover, cGAS-STING-dependent IFN-I production has been implicated in numerous infection models including herpes simplex virus, adenovirus, cytomegalovirus, Kaposi’s sarcoma-associated herpesvirus as well as retroviruses including HIV-1 and HIV-2." (PMID 31877196, 2019). "In vivo, mice deficient in Tlr9, cGas, or Sting blocked the production of type I IFNs and showed higher viral loads and serious pathology in the liver and spleen, and were more susceptible to lethality caused by infections with ECTV as compared with WT mice." (PMID 29963044, 2018). "Numerous DNA viruses have been reported to activate the cGAS–STING pathway, and cGAS or STING deficient mice are more susceptible to lethal infection after exposure to many DNA viruses, including herpes simplex virus 1 (HSV-1), vaccinia virus, and murine gammaherpesvirus 68 (MHV68)." (PMID 30114241, 2018). "Furthermore, we evaluated whether ROP5 controls the infection of PRU through cGAS-STING signaling by infecting cGAS-STING pathway-deficient cells with PRUΔROP5." (PMID 39457045, 2024). "Previous studies have shown that PCV2 Cap inhibits IFN-I induction by targeting cGAS, thereby promoting secondary infections." (PMID 40523029, 2025). "cGAS can nonetheless also restrict viral RNA replication by sensing the accumulation of mitochondrial DNA (mtDNA) in the cytoplasm due to infection." (PMID 39836220, 2025). "In mouse infection models, IRF3−/−- and IFNAR−/−-deficient mice exhibited increased susceptibility to L. pneumophila, and bacterial loads increased in cGAS−/− and TMEM173−/− mice intranasally infected with L. pneumophila compared to wild-type mice." (PMID 40137714, 2025). "Capsid structural integrity apparently influences the degree to which cGAS recognizes viral DNA, as specific CA mutations and CA-binding proteins are linked with increased or decreased IFN responses during infection." (PMID 39874383, 2025). "While osteoclasts display minimal constitutive protein expressions of RIG-I and cGAS, the levels of both were significantly upregulated following infection with S. aureus strain UAMS-1 in a dose-dependent manner." (PMID 40135931, 2025). "In the early phase of infection, the virus can suppress cGAS-STING signaling to avoid immune detection." (PMID 40072090, 2025). "Activation of cGAS-STING pathway initiates a pro-inflammatory response with the purpose of fighting the infection and repairing the damage." (PMID 41139159, 2025). "cGAS is responsible for the innate immune response to cytosolic and nuclear DNA released from DNA viruses and retroviruses upon infection or produced in actively infected cells." (PMID 40006739, 2025). "To prove that the results were specific to ASFV infection, we used PRV, which also activates the cGAS-STING pathway in the early stages of infection, to infect PAMs for 3 h, finding that the phagocytic ability did not change." (PMID 40503879, 2025). "Among these receptors, the cGAS-STING pathway plays a critical role in the innate response to infections." (PMID 40072090, 2025). "cGAS KO only moderately reduced ISRE promoter activation by HIV-1 F191A Nef infection, while type I IFN signaling was almost completely abrogated upon MAVS KO." (PMID 41354661, 2025). "Specifically, the role of the cGAS-STING signaling pathway in activating antiviral responses within chicken cells following MVA infection has yet to be thoroughly investigated." (PMID 40981440, 2025). "During stimulation or infection, nuclear cGAS is activated and translocates from the nucleus to the cytoplasm." (PMID 39998223, 2025). "In VACV, F17 orchestrates virion assembly and immune evasion by mediating mTOR-dependent degradation of the host cyclic GMP-AMP synthase (cGAS) during late infection." (PMID 41227506, 2025). "The cGAS-STING pathway is a key mediator of the inflammatory responses following infection, cellular stress and tissue damage." (PMID 41139159, 2025).
infection (continued). "Upon infection, adenoviral DNA is released into the cytoplasm, which is sensed by cGAS, activating the STING signaling pathway." (PMID 40697819, 2025). "During the early phase of infection, the virus suppresses cGAS-STING signaling to evade immune detection." (PMID 40072090, 2025). "In contrast, infection of THP-1 cells with HIV-1 containing a processing-defective Gag polyprotein, which causes capsid destabilization, triggers more robust cGAS-STING pathway activation compared to the wild-type virus." (PMID 41373786, 2025). "These point out a possible rescue effect of the cGAS inhibitor RU.521 in the first hours after infection, which seems to be able to reduce the inflammatory effect activated by SARS-CoV-2 infection." (PMID 41139159, 2025). "Evidently, infection in the presence of the capsid-destabilizing small molecule PF-74 induces a more pronounced cGAS-dependent IFN response." (PMID 41373786, 2025). "Upon infection with the parasite Plasmodium and Toxoplasma, cGAS senses parasitic genomic DNA and restricts parasite proliferation by activating signaling cascades and inducing IFN-Is." (PMID 40470467, 2025). "A recent study has shown that a high-lactate environment induced by infection promotes the Kla modification of cyclic GMP-AMP synthase (cGAS), abolishing its DNA-sensing capability." (PMID 41285721, 2025). "Among these, cGAS is a key component of the DNA-sensing pathway, playing an essential role in initiating innate immune responses to infections and cellular damage." (PMID 41153813, 2025). "On one hand, its protective role manifests during the adaptive immune phase: in blood-stage infection, parasite-derived DNA is sensed by cytosolic cGAS in host cells, providing critical immune stimulation for downstream B cell responses." (PMID 41438738, 2025). "The Bray–Curtis (the differences demonstrated by distances to the axis) and LEfSe analyses (the representative bacteria for the group) demonstrated differences between WT and cGAS-/- mice after infection." (PMID 41300373, 2025). "Infection with the SIRV strain rSC0163 resulted in increased protein expression of cGAS, p-STING, p-TBK1, and p-IRF3 compared with infection by the non-SIRV strain rSC0162." (PMID 40876118, 2025). "Following infection with Nipah virus and measles virus, both cGAS and IFI16 activate STING, leading to the production of IFNβ." (PMID 40006739, 2025). "During infection with Pseudomonas aeruginosa (P. aeruginosa), the cGAS-STING pathway is activated by P. aeruginosa DNA to induce type I IFNs." (PMID 40137714, 2025). "With infection, in platelets, associations changed and expression of F2RL3 and GP6 both positively correlated with TLR6, TLR9, RIG-I, MDA5, LGP2, and CGAS." (PMID 40825056, 2025). "During infections with Pseudomonas aeruginosa and Mycobacterium tuberculosis, cGAS senses bacterial genomic DNA to initiate selective autophagy, leading to bacterial clearance." (PMID 40470467, 2025). "During infection with COVID-19, aberrant cGAS-STING activation driven by cytosolic DNA (potentially from host cell damage) contributes to the production of IFN-I and pro-inflammatory cytokines, aggravating the infection in the lungs." (PMID 40872644, 2025). "Another possibility is that infection of macrophages with L. interrogans results in mitochondrial stress resulting in the release of mtDNA which can then activate cGAS-STING." (PMID 40501870, 2025). "In the presence of Vpx, comparable levels of cGAS-STING pathway activation were observed upon infection with both HIV-1 and HIV-2, and a comparable decrease in such activation was observed upon NONO depletion." (PMID 41373786, 2025). "The results indicate that LSDV ORF137 inhibits the transcription of IFN-β, ISG54, ISG56, and Mx-1 genes induced by cGAS-STING in HEK-293T cells post-HSV-GFP-infection." (PMID 41002440, 2025).